SPINK9 (serine peptidase inhibitor Kazal type 9)
Description:
Serine protease inhibitor which specifically inhibits KLK5. May contribute to the regulation of the desquamation process in skin by inhibiting KLK5.
Synonyms: LEKTI2
Tractability: Antibody: UniProt places it where antibodies can reach, with high confidence; its Gene Ontology location is reachable by antibodies, with high confidence; UniProt predicts a signal peptide or a membrane-spanning region.
Gene: Protein-coding gene on chromosome 5 (148,321,203 to 148,339,852, forward strand). Ensembl gene ENSG00000204909.
Subcellular location: Secreted
Subcellular location (Human Protein Atlas): Nucleoplasm; Vesicles; Predicted to be secreted
Pathways (Reactome):
Developmental Biology: Formation of the cornified envelope
Gene Ontology:
Molecular function: protein binding; serine-type endopeptidase inhibitor activity
Biological process: negative regulation of proteolysis
Cellular component: extracellular region
Genetic constraint (gnomAD): Loss-of-function variants: 2 observed, 6.78 expected, observed/expected ratio (o/e) 0.3, 90% interval 0.12 to 0.93. That is too few expected variants to judge how well the gene tolerates losing a copy. Missense variants: 48 observed, 45.08 expected, observed/expected ratio (o/e) 1.06, 90% interval 0.84 to 1.35. Synonymous variants: 13 observed, 15.14 expected, observed/expected ratio (o/e) 0.86, 90% interval 0.56 to 1.36.
Homologues: Orthologues: macaque SPINK9 (90% identical), chimpanzee SPINK9 (81% identical), dog SPINK9 (65% identical), pig SPINK9 (59% identical), rabbit SPINK9 (58% identical), rat Spink10 (29% identical), mouse Spink10 (27% identical), mouse Spinkl (26% identical), mouse Spink11 (24% identical). Paralogues in human: SPINK7 (37% identical), SPINK14 (30% identical), SPINK13 (28% identical), SPINK2 (28% identical), SPINK8 (24% identical).
Diseases named in the same sentence as SPINK9 in open-access papers:
SPINK9 is named in the same sentence as 10 diseases in open-access papers, as found by Europe PMC text mining. Sharing a sentence is not in itself a finding about the gene and the disease. The quoted sentences say what the papers report.
atopic dermatitis (1 paper, 2017). "SPINK6 and SPINK9 are also expressed in the skin, and altered expression levels are associated with atopic dermatitis or psoriasis." (PMID 28554943, 2017).
hyperlipidemia (1 paper, 2022). "Analysis of upregulated DEGs has shown that the following seven genes were common between all complications of TIDM (hyperlipidemia, neuropathy, ketoacidosis, hypothyroidism and PCOS): SPINK9, TRDN, PVRL4, MYO3A, PDLIM1, KIAA1614 and GRP." (PMID 36175575, 2022). "Assessment of the relative fold-change of the seven upregulated genes in different T1DM complications showed a significant increase in expression of SPINK9 in T1DM complications compared to DWC, hyperlipidemia (5.28), neuropathy (3.79), ketoacidosis (5.20), hypothyroidism (3.79) and PCOS (5.20)." (PMID 36175575, 2022).
squamous cell carcinoma (1 paper, 2022). A carcinoma arising from squamous epithelial cells. "In fact, some scholars have observed that SPINK9 is expressed not only in healthy palm and plantar skin but also in chronic simple lichens, actinic keratosis and squamous cell carcinoma." (PMID 35223512, 2022). "However, the significance of SPINK9 expression in squamous cell carcinoma is unknown." (PMID 35223512, 2022).
tumor (1 paper, 2022). "In view of the inhibitory effect of SPINK9 on KLK5, we believe that SPINK9 is a potential tumor-influencing factor." (PMID 35223512, 2022).
SPINK9 also shares sentences with these, for which no sentence is quoted: hypothyroidism (1 paper); inflammatory skin disease (1); Insulin resistance (1); neuropathy (1); psoriasis (1); type 2 diabetes mellitus (1).